CDH1 (cadherin 1)
Diseases named in the same sentence as CDH1 in open-access papers (continued):
Sharing a sentence is not in itself a finding about the gene and the disease.
pancreatitis (10 papers, 2009 to 2024). Inflammation of the pancreas. "Cdh1-deficient organoids were collapsed, as expected from loss of cell adhesion, and showed signs of apoptosis, which morphologically appeared similar to pancreatitis." (PMID 32231028, 2020). "Similarly, we found that Cdh1 deletion in the pancreas induced pancreatitis-like phenotypes, as well as an increase in the transcription of YAP targets." (PMID 30194315, 2018).
small cell lung carcinoma (10 papers, 2010 to 2024). Small cell lung cancer (SCLC) is a highly aggressive malignant neoplasm, accounting for 10-15% of lung cancer cases, characterized byrapid growth, and early metastasis. "CTNNB1 and CDH1 were expressed in 90% (54/60) of small cell lung cancer cells, in which weak expression (score between 10 and 20) was 11.11%, moderate (score between 20 and 100) was 70.37% and strong (score between 100 and 300) was 18.52%." (PMID 29115924, 2017).
Cirrhosis (9 papers, 2015 to 2022). A chronic disorder of the liver in which liver tissue becomes scarred and is partially replaced by regenerative nodules and fibrotic tissue resulting in loss of liver function. "Human cirrhotic and cirrhosis-associated HCC tissues showed an increase of IMP2 expression and of the progenitor cell markers SOX9, SPP1/osteopontin, CDH1/E-cadherin, AFP, PROM1/CD133, BEX1, EPCAM." (PMID 31555647, 2019).
Cowden syndrome (9 papers, 2016 to 2025).
gastritis (9 papers, 2013 to 2026). Inflammation of the stomach. "We hypothesize that this mutation by introducing a CpG island in the CDH1 promoter region increases the probability of CDH1 hypermethylation, a well known event favouring the transcriptional inactivation, an early event in HP gastritis and a key risk factor associated to GC development." (PMID 24204729, 2013).
seminoma (9 papers, 2005 to 2023). A radiosensitive malignant germ cell tumor found in the testis (especially undescended), and extragonadal sites (anterior mediastinum and pineal gland). "We previously demonstrated that nuclear PTTG1 promotes seminoma tumor invasion through its transcriptional activity on matrix metalloproteinase 2 (MMP-2) and E-cadherin (CDH1)." (PMID 38069214, 2023).
chronic gastritis (8 papers, 2012 to 2025). Inflammation of the stomach that is chronic in nature. "It has been reported that H. pylori infection is associated with CDH1 methylation in chronic gastritis patients." (PMID 25184143, 2014). "It was reported that methylation of the CDH1 gene promoter is a frequent event in samples from H. pylori infected patients with chronic gastritis, suggesting that CDH1 inactivation is an early step toward gastric tumorigenesis." (PMID 31781079, 2019). "Furthermore, background alterations in CDH1-carriers make it even more difficult to discover cancer lesions: Chronic gastritis, foveolar hyperplasia, cystic gland dilatation and epithelial tufting, as well as globoid change, have been described in CDH1-carriers." (PMID 35887173, 2022). "More recently, we reported that the long-term use of aspirin for more than 3 years decreases CDH1 methylation in non-IM and CIMP in IM in patients with chronic gastritis who regularly took aspirin for more than 3 years, but was not very effective in reversing the methylation that occurred in IM43." (PMID 30254207, 2018).
cleft palate (8 papers, 2014 to 2024). Cleft palate is a fissure type embryopathy that affects the soft and hard palate to varying degrees. "In particular, oral facial clefts (OFC), such as cleft lip with or without cleft palate (CL/P), or cleft palate alone (CP) have been described both in HDGC family members and as independent disorders associated with CDH1 genetic alterations." (PMID 38414029, 2024).
cutaneous melanoma (8 papers, 2014 to 2025). A primary melanoma arising from atypical melanocytes in the skin. "In the publicly available GENIE dataset, looking exclusively at cutaneous melanomas shows that the specific mutation rates within primary tumors were 55 % for TERT, 40 % for BRAF, 7.2 % for KIT, 2.5 % for NRAS, and 1.9 % for CDH1." (PMID 38158497, 2024). "The exceptions were testicular germ cell tumors and thymoma, in which CDH1 mRNA was upregulated, and skin cutaneous melanoma, in which CDH1 mRNA was downregulated compared to corresponding normal tissue." (PMID 37189027, 2023).
Familial adenomatous polyposis (8 papers, 2015 to 2025). Familial adenomatous polyposis (FAP) is characterized by the development of hundreds to thousands of adenomas in the rectum and colon during the second decade of life. "Epstein–Barr virus infection, autoimmune gastritis, germline mutations in the CDH1 gene, polymorphism in the prostate stem cell antigen, and familial adenomatous polyposis are known to be associated with HpUIGC." (PMID 38542051, 2024).
hereditary cancer syndromes (8 papers, 2015 to 2025).
kidney stone (8 papers, 2013 to 2023). "Abnormal CDH1 expression has been linked to many human diseases including cancer, nephrolithiasis, pre-eclampsia, and ectopic pregnancy." (PMID 27689323, 2016). "Patients having CA genotype of rs16260 CDH1 polymorphism were associated with an almost trifold increased risk for developing kidney stone than those with the AA genotype (95 % CI 1.08–7.28, OR 2.8, P = 0.033)." (PMID 27733975, 2016). "Abnormal CDH1 expression has been linked to many human diseases, including tumors, nephrolithiasis, pre-eclampsia, and ectopic pregnancy." (PMID 24838934, 2014). "We further evaluated the effect of CDH1-160C>A polymorphism on nephrolithiasis risk stratified by age, sex, and BMI." (PMID 24023817, 2013). "Stratified analyses on association between the CDH1-160C>A polymorphism and risk of nephrolithiasis." (PMID 24023817, 2013). "In this hospital-based case-control study, we investigated the association of the CDH1-160C>A polymorphism and risk of nephrolithiasis in a Chinese population." (PMID 24023817, 2013). "Distribution of genotypes of CDH1-160C>A polymorphism and their associations with risk of nephrolithiasis." (PMID 24023817, 2013). "Our results suggest that the CDH1 polymorphism is involved in the etiology of nephrolithiasis and thus may be a marker for genetic susceptibility to nephrolithiasis." (PMID 24023817, 2013). "Deregulation of CDH1 in conjunction with renal cell injury, caused by oxalate crystals may contribute to the development of nephrolithiasis." (PMID 24023817, 2013). "Therefore, large population-based prospective studies with ethnically diverse populations are warranted to further elucidate the impact of CDH1 polymorphism on nephrolithiasis susceptibility." (PMID 24023817, 2013). "To test this hypothesis, we investigated the correlation of CDH1 gene polymorphism with risk of nephrolithiasis in a case-control study in a Chinese population." (PMID 24023817, 2013). "Regulatory variants of rs16260 of the CDH1 gene may confer susceptibility to nephrolithiasis." (PMID 27733975, 2016). "Because the CDH1 gene is responsible for Ca2+-dependent cell-cell adhesion and plays an important for the establishment and maintenance of normal epithelial polarity and organization, we hypothesized that the CDH1-160C>A polymorphism is associated with risk of nephrolithiasis." (PMID 24023817, 2013). "We hypothesized that variants in the CDH1 gene are associated with risk of nephrolithiasis." (PMID 24023817, 2013). "Other polymorphisms, such as in the CDH1, VEGF, IL18, IL1RA, MnSOD, ORAI1, and TAP genes, have also been reported to be associated with kidney stone recurrence." (PMID 33956883, 2021). "However, the association of rs5030625 (CDH1-347G > GA) regulatory polymorphism with noncancerous nephrolithiasis has not been investigated in any known studies, thus we were unable to compare our results with those of similar studies covering other ethnic populations." (PMID 27733975, 2016). "E-cadherin (CDH1) is involved in epithelial cell-cell interactions and plays important roles in the etiology of nephrolithiasis." (PMID 24023817, 2013).
kidney tumors (8 papers, 2007 to 2023). "Previous studies have shown that HIF can mediate suppression of CDH1 gene transcription, and result in the downregulation of E-cadherin in VHL-deficient kidney tumor tissues." (PMID 37201027, 2023). "Significant differences in methylation levels among the four subtypes of renal tumors were found for CDH1 (p = 0.0007), PTGS2 (p = 0.002), and RASSF1A (p = 0.0001)." (PMID 17645803, 2007). "In conclusion, we found that a gene panel including CDH1, PTGS2, and RASSF1A which might contribute to a more accurate detection and discrimination of the common renal tumors." (PMID 17645803, 2007).
liposarcoma (8 papers, 2012 to 2025). A usually painless malignant tumor that arises from adipose tissue. "In a previous large-scale genomic sequencing study of soft tissue sarcoma specimens, that included 50 DD liposarcomas, a different CTNNB1 (T41I) mutation was described in a DD liposarcoma, including 3 other nonrecurring mutations (CDH1 (N238D), EPHA1 (A2127) and FBXW7 (E113fs))." (PMID 29731991, 2018).
mesenchymal tumor (8 papers, 2006 to 2025). "In the third category there were seven studies on epithelial mesenchymal transition (EMT)/TGFb/mesenchymal tumor (EMT/TGFb/Mes) according to the authors, with specific genes CDH1,2, VIM, and TGFb1,2,3 in studies as follows: E16 (CDH1,2, TGFb1, VIM), E24 (TGFb1), E31, E38, E39, E43 (CDH2), and E46." (PMID 40867621, 2025). "PANC1 cells grown in conditioned media also showed a decrease in the expression of E-cadherin (CDH1) and an increase in expression of zinc finger E-box binding homeobox 1 (ZEB1) and vimentin (VIM), pointing to a PAR1/macrophage-induced mesenchymal tumor state in PDAC." (PMID 34066284, 2021).
metastatic prostate carcinoma (8 papers, 2015 to 2023). A carcinoma that arises from the prostate gland and has spread to other anatomic sites. "In fact, SPOP-mutated metastatic prostate cancers are strongly enriched for CDH1 loss; these tumors appear to be highly sensitive to Abiraterone treatment." (PMID 31366128, 2019).
preeclampsia (8 papers, 2017 to 2025). Preeclampsia is a hypertensive disorder of pregnancy that is characterized by new-onset hypertension with proteinuria presenting after 20 weeks of gestation, and depending on mild or severe forms may initially present with severe headache, visual disturbances, and hyperreflexia. "In preeclampsia, however, the opposite is true; RPL39 is down-regulated and CDH1 is up-regulated, which inhibits trophoblast invasiveness." (PMID 37174083, 2023).
rectal cancer (8 papers, 2010 to 2024). A primary or metastatic malignant neoplasm that affects the rectum. "Mutation of this gene is closely associated with BRCA, rectal cancer, and other cancer types, and the expression of CDH1 is downregulated in various tumour tissues." (PMID 35785160, 2022).
tongue cancer (8 papers, 2013 to 2022). A malignant neoplasm affecting the tongue. "Ginsenoside Rd can also regulate the migration and invasion of tongue cancer cells through the H19/miR-675-5p/CDH1 axis." (PMID 36074434, 2022). "CDH1 overexpression decreased the invasion, migration, growth and number of clones in tongue cancer cells." (PMID 36074434, 2022). "Therefore, CDH1 was overexpressed to further study the relationship between E-cadherin and metastasis of tongue cancer." (PMID 36074434, 2022). "Ginsenoside Rd inhibits tongue cancer cell migration and invasion via the H19/miR-675-5p/CDH1 axis." (PMID 36074434, 2022). "Compared to the control group, CDH1 knockdown increased the migration, invasion, growth and number of clones of SCC9, indicating that E-cadherin is closely associated with the metastasis of tongue cancer." (PMID 36074434, 2022). "CDH1 knockdown increased the migration and invasion ability of tongue cancer cells." (PMID 36074434, 2022). "Moreover, H19 and CDH1 may be potential markers of tongue cancer." (PMID 36074434, 2022).
gynecological cancers (7 papers, 2010 to 2023). "CTNNA1, CTNNB1 and CDH1 expressions were found to be suppressed in EC as well as other gynecological cancers, and further decreased with advanced invasion, contributing to cell-to-cell junctional dysfunction." (PMID 37313172, 2023).
keloid (7 papers, 2015 to 2024). An irregularly shaped, elevated mark on the skin caused by deposits of excessive amounts of collagen during wound healing. "Although CDH1 gene expression levels are similar between normal and keloid keratinocytes, keloids express decreased protein levels of E-cadherin, in line with cadherin switching from E-cadherin to mesenchymal markers such as N-cadherin, fibronectin-1, vimentin, and cadherin-11." (PMID 31440236, 2019).
leiomyoma (7 papers, 2014 to 2025). A well-circumscribed benign smooth muscle neoplasm characterized by the presence of spindle cells with cigar-shaped nuclei, interlacing fascicles, and a whorled pattern. "In one case, neither of the found P/LP variants explained the phenotype: a patient with FH-deficient leiomyoma had P/LP variants in CDH1 and ATM (case #16)." (PMID 40943312, 2025). "Many proteins such as F3, WNT2, CDH1, and LIF shown in the protein–protein interaction networks are well known in leiomyoma pathogenesis, and others, such as ICAM1, CXCL8, CCL2, and NANOG are novel and require further investigation." (PMID 36835153, 2023).
leiomyosarcoma (7 papers, 2012 to 2021). An uncommon, aggressive malignant smooth muscle neoplasm, usually occurring in post-menopausal women. "Silencing the SNAI2 gene could significantly upregulate the expression of CDH1, downregulate the expression of vimentin and CDH2 in leiomyosarcoma cells, and significantly impair the proliferation and invasiveness of cells." (PMID 31749661, 2019).
ovarian endometriosis (7 papers, 2014 to 2025). A non-neoplastic disorder characterized by the growth of endometrial tissue in the ovaries. "A few studies have reported significantly increased expression of CDH1 in the normal uterine endometrium in the secretory phase compared to in ovarian endometriosis." (PMID 37047609, 2023). "Unexpectedly, EEC16 did also not express E-Cadherin, and so we analyzed expression of the CDH1 gene in primary human ovarian endometriosis tissues and normal endometrial biopsies." (PMID 24502583, 2014).
uveal melanoma (7 papers, 2009 to 2025). A melanoma derived from melanocytes of the uveal tract. "Another study had screened CDH1 as predictive of primary uveal melanoma metastasis." (PMID 38767825, 2024). "Interestingly, expression profiling using a 12‐gene assay reliably distinguished metastasising from non‐metastasising uveal melanomas in humans and four of these genes (HTR2B, FXR1, LTA4H, and CDH1) are overexpressed in metastasising canine uveal melanoma." (PMID 32652526, 2020).
B-cell lymphoma (6 papers, 2005 to 2025). "The gene promoters of BMPER, CDH1 and LRP12 were methylated in all analyzed B-cell lymphoma cell lines across all subtypes." (PMID 25226156, 2014). "We focused on major types of B-cell lymphoma (BL, DLBCL ABC, DLBCL GCB, FL and PMBL) and demonstrated that the gene promoters of LRP12 (94%), CDH1 (92%), and BMPER (58%) were methylated at a high frequency, whereas DUSP4 and BMP7 showed lower methylation frequencies (32% and 22%, respectively)." (PMID 25226156, 2014).
cervical tumor (6 papers, 2013 to 2021). "Several human genes that encode functional inhibitors of the Wnt pathway have been reported to be methylated in cervical tumors including WIF1, CDH1, FHIT, APC, the SLIT2/ROBO family and the SRFP family." (PMID 25826459, 2015).
chronic pancreatitis (6 papers, 2012 to 2025). A chronic inflammatory process causing damage and fibrosis of the pancreatic parenchyma.
clear cell carcinoma (6 papers, 2011 to 2021). "Five most downregulated genes in clear cell carcinoma include, ITGB6 (−9.09-fold), MUC1 (−5.00-fold), CDH1 (−3.57-fold), HIF1A (−2.27-fold) and FOS (−1.96-fold)." (PMID 30863721, 2019).
diffuse gastric adenocarcinoma (6 papers, 2012 to 2025). An adenocarcinoma arising from the stomach. "Inactivation of CDH1/E-cadherin occurs through epigenetic silencing or somatic mutations, which promote the invasiveness of diffuse gastric adenocarcinoma." (PMID 41300276, 2025). "We found two CDH1 mutations (V832L and A324V) linked to hereditary diffuse gastric adenocarcinoma that confer binding to the WW domain of the HECT type E3 ligase SMURF2, and a R794W mutation that creates an ATG8 binding site." (PMID 39009827, 2024). "Hereditary diffuse gastric adenocarcinomas, observed in a minority of cases, exhibit autosomal dominant inheritance and are associated with mutations in E-cadherin (CDH1) gene." (PMID 36846589, 2023).
intrahepatic cholangiocarcinoma (6 papers, 2019 to 2024). A carcinoma that arises from the intrahepatic bile duct epithelium in any site of the intrahepatic biliary tree. "In intrahepatic cholangiocarcinoma (ICC), addition of Ang II resulted in alterations in expression of EMT markers, decrease of CDH1 and increase of vimentin expression level." (PMID 33673178, 2021).
mucinous adenocarcinoma (6 papers, 2010 to 2022). An invasive adenocarcinoma composed of malignant glandular cells which contain intracytoplasmic mucin. "Similarly, the CDH1 (Leu452Arg) variant was identified in mucinous adenocarcinoma and adenomatous polyp samples in ∼13% (11/87) and ∼19% (10/54) of reads for the locus, respectively." (PMID 35483879, 2022).
Pleural effusion (6 papers, 2019 to 2023). The presence of an excessive amount of fluid in the pleural cavity.
retinoblastoma (6 papers, 2016 to 2024). A malignant tumor that originates in the nuclear layer of the retina. "However, this does not directly discriminate CDH1 and CDH8 as retinoblastoma suppressors, and these discrepancies signify the difficulty of pinpointing a single gene as driver." (PMID 27126562, 2016).
tongue squamous cell carcinoma (6 papers, 2013 to 2017). A squamous cell carcinoma that arises from the tongue. "We evaluated and statistically analyzed the clinicopathological factors and mRNA expressions of Cox-2, CDH-1 and its repressors in surgical specimens of 40 patients with tongue squamous cell carcinoma (TSCC)." (PMID 24887090, 2014).